ATF3 (activating transcription factor 3)
Diseases named in the same sentence as ATF3 in open-access papers (continued):
Sharing a sentence is not in itself a finding about the gene and the disease.
colorectal cancer (continued). "Importantly, GDF-15 promoter is activated by CHOP and activating transcription factor 3 (ATF3) in NSAIDs sulindac sulfate-treated colorectal cancer cell lines such as HCT11632." (PMID 36008442, 2022). "Likewise, a recent study suggested the ATF3-mediated pathway as a possible mechanism of PFF-A-induced apoptosis in human colorectal cancer cells." (PMID 34199834, 2021). "Phlorofucofuroeckol A, a phlorotannin present in the brown alga E. bicyclis, exhibited antiproliferative and proapoptotic properties in human cancer cells (LoVo, HT-29, SW480 and HCT116) by activating the transcription factor 3 (ATF3)-mediated pathway in human colorectal cancer cells." (PMID 33007997, 2020). "Therefore, we measured the expression of ATF3 mRNA and protein in response to treatment with both splicing inhibitors in colorectal carcinoma and cervical carcinoma cells (HCT116 and HeLa cells, respectively)." (PMID 33370278, 2020). "Moreover, NSAIDs increased ATF3 expression and consequently repressed invasive ability of human colorectal cancer cells." (PMID 31410216, 2019). "ATF3 is a candidate biomarker and target for human colorectal cancer treatment and prevention." (PMID 29966001, 2018). "ATF3/CREB activation induces apoptosis in HCT116 human colorectal cancer cells." (PMID 30060617, 2018). "We studied the biological role of ATF3 in human colorectal cancer cells." (PMID 29966001, 2018). "Therefore, we examined if TC-HW-induced ROS directly affects the activation of NF-κB and ATF3, which induces apoptosis in human colorectal cancer cell." (PMID 29554905, 2018). "In colorectal cancer, ATF3 activates DR5 to enhance sensitivity to apoptotic cell death." (PMID 28860159, 2017). "Thus, in this study, we investigated the molecular mechanism of PFF-A-mediated ATF3 expression and apoptosis in human colorectal cancer cells." (PMID 27043582, 2016). "Tumor pairs from seven patients (five with colorectal cancer, one with sarcoma, and one with adrenal cancer) passed quality control by standard hematoxylin and eosin staining for tumor content, and were evaluable for ATF-3 IHC." (PMID 25777468, 2015). "Indeed, there is a report that ROS induced ATF3-mediated apoptosis in human colorectal cancer cells." (PMID 24962785, 2014). "In addition, it induced cell growth arrest and apoptosis by activating ATF3 expression and cyclin D1 proteasomal degradation in colorectal cancer cells, SW480." (PMID 24962785, 2014). "Up-regulation of ATF3 expression can induce apoptosis in colorectal cancer cells." (PMID 24962785, 2014). "This indicates that ATF3 may be an important molecular target of cancer chemoprevention against human colorectal cancer." (PMID 25494848, 2014). "Since there is growing evidence that ATF3 is associated with to cell growth arrest and apoptosis in human colorectal cancer cells, we evaluated whether GL affects ATF3 expression in HCT116 and SW480 cells." (PMID 25338635, 2014). "In addition, it was reported that anti-cancer agents such as indole-3-carbinol, conjugated linoleic acid, epicatechin gallate, tolfenamic acid and PI3 kinase inhibitor induce ATF3-dependent apoptosis in colorectal cancer cells." (PMID 25338635, 2014). "Thus, up-regulation of ATF3 and down-regulation of cyclin D1 are major molecular targets for treatment of colorectal cancer." (PMID 24962785, 2014). "In our study, GL increased the PARP cleavage and reduced the viability of colorectal cancer cells, indicating that increased apoptosis and reduction of cell viability may be mediated by activation of ATF3 expression in GL-treated cells." (PMID 25338635, 2014). "There is a growing body of evidence that ATF3 expression could induce apoptosis in human colorectal cancer cells." (PMID 25494848, 2014).
colorectal cancer (continued). "In conclusion, ginger leaves may induce apoptosis and reduction of cell viability, followed by the increased ATF3 expression via activating ATF3 promoter in human colorectal cancer cells." (PMID 25338635, 2014). "In human colorectal cancer, ATF3 expression was suppressed compared to normal adjacent tissue." (PMID 24962785, 2014). "Our data suggest that induction of ATF3 may be valuable for improving therapy of colorectal cancer patients in terms of preventing hepatic and peritoneal metastasis." (PMID 21129190, 2010). "Furthermore, ATF-3 is upregulated in HCT-116 human colorectal cancer cells following treatment with PPAR-γ agonist troglitazone, nonsteroidal anti-inflammatory drugs, diallyl disulfide, and resveratrol." (PMID 17764562, 2007). "Here, using single-cell RNA sequencing, we classified proliferating and quiescent cancer cell populations in the human colorectal cancer spheroid model and identified ATF3 as a novel signature of QCCs that could support cells living in a metabolically restricted microenvironment." (PMID 37833290, 2023). "In human colorectal cancer cells, the ethyl acetate fraction of 80% methanol extract obtained from the plant parts of A. distichum including the flower, leaf, and branch induced transcriptional activation of activating transcription factor 3 (ATF3), resulting in apoptosis induction." (PMID 32560393, 2020). "However, our knowledge of Wnt-dependent ATF3 gene expression and its biological role in human colorectal cancer is unknown." (PMID 29966001, 2018). "Hence, ATF3 might mediate tumor suppression through various signaling pathways in human colorectal cancer." (PMID 29966001, 2018). "In addition, the cell viability was reduced and apoptosis was induced in human colorectal cancer cells by the extracts of ginger leaf dose-dependently, and the effects resulted from activation of ATF3 promoter and following increase of ATF3 expression through ERK1/2 activation." (PMID 27529277, 2016). "Therefore, it is suggested that ATF3 activation may be a promising cancer preventive and therapeutic target in human colorectal cancer." (PMID 25494848, 2014). "Therefore, it is thought that quercetin may be responsible for ATF3-mediated apoptosis by ginger leaves in human colorectal cancer cells and quercetin of GL may be absorbed in the intestinal lumen and plasma of animal." (PMID 25338635, 2014). "Furthermore, our study provides evidence that such ATF3-induction can be achieved by Hsp90-inhibition, which is particularly interesting since Hsp90-inhibitors are promising new agents for targeted therapy of advanced colorectal cancer and other malignancies." (PMID 21129190, 2010). "Our study delves into the intricate regulatory mechanisms of Activating transcription factor 3 (ATF3) on Cystathionine β-synthase (CBS) under cystine deprivation stress, conferring resistance to ferroptosis in colorectal cancer (CRC) cells." (PMID 38490069, 2024). "Mechanically, we demonstrated that ATF3 promoted FOXP4-AS1 expression, which exacerbates colorectal cancer progression via the miR-423-5p/NACC1 axis." (PMID 35034547, 2022). "Ginger leaves extract induced apoptosis in human colorectal cancer cells, HCT116, SW480 (human colon adenocarcinoma cells), and LoVo by activating transcription factor 3 (ATF3)." (PMID 35846992, 2022). "ATF3 upregulation under stress was proven to be mediated exclusively by the p38 signaling pathway in HeLa cells, while through ERK, SAPK and p38 in colorectal cancer." (PMID 33050633, 2020). "Our present study clearly showed that the stress response gene ATF3 is a direct target for TCF4/β-catenin binding and plays a role in the suppression of cancer cell invasion and migration in human colorectal cancer cells." (PMID 29966001, 2018). "In another respect, ATF3 has been described to mediate anti-neoplastic and anti-invasive effects of non-steroidal anti-inflammatory drugs (i.e. COX-2 inhibitors) in colorectal cancer." (PMID 21129190, 2010).
colorectal cancer (continued). "Collectively, the findings reveal that the ATF3-CBS signaling axis is the primary feedback pathway in ferroptosis, and blocking this axis could be a potential therapeutic approach for colorectal cancer." (PMID 38490069, 2024). "In addition, ROS increase the expression of activating transcription factor 3 (ATF3) and ROS-mediated ATF3 activation induces apoptosis in human colorectal cancer cells." (PMID 29554905, 2018). "Indeed, ERK expression was up-regulated by NF-κB and activating transcription factor 3 (ATF3) activation, which was followed by an increase in apoptosis in human colorectal cancer cells." (PMID 28125661, 2017). "Moreover, ATF3 expression plays an important role in apoptosis induced by a variety of anti-cancer compounds such as berberine, conjugated linoleic acid, curcumin and 3,3′-diindolylmethane in human colorectal cancer cells, which indicates that ATF3 could function as a pro-apoptotic mediator." (PMID 24962785, 2014). "It was reported that ATF3 over-expression resulted in increased apoptosis of PC3 human prostate cancer cells, reduced focus formation, and reduced size of subcutaneous HCT-116 human colorectal cancer cell xenografts in nude mice." (PMID 25149542, 2014). "However, in this study, it was clearly shown that ATF3 is a direct target of β-catenin/TCF4 binding, leading to the possibility that ATF3 is activated by both MAPK/JNK and Wnt signals to mediate their biological functioning in colorectal cancer in a context-dependent manner." (PMID 29966001, 2018). "DHTS could increase ATF3 expression contributing to DHTS-induced apoptosis in both non-malignant SW480 and malignant SW620 colorectal cancer cells." (PMID 29441017, 2018).
prostate carcinoma (57 papers, 2009 to 2025). A carcinoma that arises from epithelial cells of the prostate gland. "For example, ATF3 functions as an oncogene in prostate cancer, where its high expression is associated with increased cell proliferation in response to androgen stimulation." (PMID 38586033, 2024). "In accordance with the ex vivo and in vivo models, the authors observed that patients with prostate cancer who had higher ATF3 levels were associated with improved overall survival." (PMID 37104249, 2023). "Analysis of transcriptional profiles from primary human prostate cancers revealed that high levels of ATF3 levels are associated with improved overall survival." (PMID 37104245, 2023). "ATF3 expression was related to glycosaminoglycan degradation, pathways in cancer, prostate cancer, and TGF-β signaling, and DUSP1 was associated with adipocytokine signaling, graft vs. host disease, pathways in cancer, and small cell lung cancer." (PMID 35372438, 2022). "For instance, the loss of ATF3 was found to promote prostate cancer development, but the overexpression of ATF3 enhanced the metastasis of prostate cancer." (PMID 33539340, 2021). "Elevated ATF3 expression has been correlated with poor prognosis in prostate cancer and has been associated with increased proliferation and metastasis formation." (PMID 33050633, 2020). "Research demonstrated the loss of ATF3 promotes prostate cancer progression of in PTEN knockout mice through activating AKT pathway." (PMID 31410216, 2019). "It is known to negatively regulate cyclin D1 and loss of ATF3 was recently shown to promote prostate cancer in a transgenic mouse model." (PMID 26304929, 2015). "Therefore, we examined the relationship between PRC2 transcriptional signatures and ATF3-trancriptional signatures in multiple prostate cancer mRNA datasets, to determine if there was an association between effective PRC2 derepression and ATF3 activity." (PMID 37104245, 2023). "Additionally, the knockdown mutation of ATF3 promotes the development of prostate cancer through activation of PI3K/Akt signaling, which is crucial for the growth, survival, and development of prostate cancer cells and suggests that ATF3 is a promising cancer preventive-therapeutic target." (PMID 32560393, 2020). "For instance, ATF3 has been reported to induce apoptosis and inhibit the outgrowth of prostate cancer, while simultaneously promoting the invasion of prostate cancer cells." (PMID 39789383, 2025). "Recently, the regulatory role of KLF6 in ATF3 expression was verified in endothelial cells, pancreatic cancer cells, and prostate cancer cells." (PMID 39872376, 2024). "The unbiased identification of ATF3 in this study highlights the important role that this stress response gene plays in the death of prostate cancers." (PMID 37104245, 2023). "Consistent with this notion, genetic ablation of ATF3 in genetically engineered mouse prostate cancer models has been shown to increase the rate of prostate tumor development and progression and decreases apoptosis in tumors." (PMID 37104245, 2023). "In the colon, liver, and prostate cancers, ATF3 had tumor suppression impact by apoptosis activation." (PMID 35747788, 2022). "Previous research reported that ATF3 has pro-apoptotic roles in ovarian cancer cells and suppresses prostate cancer with phosphatase and tensin homolog dysfunction." (PMID 35283423, 2022). "Consistently, in prostate cancer, ATF3 is believed to mediate the effect of androgen receptors and represses the androgen signaling required for sustaining prostate cancer cell proliferation and survival." (PMID 34728784, 2021). "Several studies corroborate obvious down-regulation and suppressive efficacy of ATF3 in carcinogenesis, including hepatocellular carcinoma, prostate cancer, and non-small cell lung carcinoma." (PMID 34098867, 2021).
prostate carcinoma (continued). "ATF3 was found to be downregulated in several human cancers, including liver cancer, colon cancer, bladder cancer, prostate cancer and other epithelial cancers." (PMID 33539340, 2021). "For example, Fos proto-oncogene, AP-1 transcription factor subunit (c-Fos), and activating transcription factor 3 (ATF3) are induced by androgen in the rat hippocampus and in human prostate cancer cells, respectively." (PMID 31963388, 2020). "The promotion of pulmonary metastasis in mice was observed after rat ATF3-overexpressing AT2.1 prostate cancer cells were injected subcutaneously into severe combined immunodeficient mice." (PMID 32922364, 2020). "Various human cancers, including liver cancer, prostate cancer, colon cancer, and multiple myeloma, exhibit a low level of ATF3 expression." (PMID 32560393, 2020). "Elevated expression levels of ATF3 have been noted in normal human prostate tissue and the androgen-dependent prostate cancer cell line LNCap, but weak expression levels of ATF3 are observed in androgen-independent cancer cells, including PC3 and DU145 cells." (PMID 32922364, 2020). "ATF3 is a crucial regulator of Kruppel-like factor 6 (KLF6)-induced apoptosis in prostate cancer cells." (PMID 32922364, 2020). "Wang and Zang provide the genetic evidence supporting the role of ATF3 as a tumor suppressor in a subset of prostate cancers with PTEN dysfunction." (PMID 31581661, 2019). "In contrast, ATF3 acts as a tumor suppressor during the apoptotic cell death of prostate cancers and the metastasis of bladder cancer cells." (PMID 29966001, 2018). "ATF3 also suppresses the development of prostate cancer induced by silencing of the tumor suppressor Pten in a mouse model, and knockdown of ATF3 expression promotes the activation of the oncogenic AKT signaling pathway." (PMID 30376856, 2018). "In particular, we predicted the nuclear receptor NR4A2 and the activating transcription factor 3 (ATF3) as novel upstream regulators of NFκB in prostate cancer." (PMID 27078000, 2016). "Our predicted NFκB pathway suggested 8 novel genes which were found to be highly down-regulated in lethal prostate cancer and highly functionally related to NFκB, namely ATF3, CXCL2, DUSP5, JUNB, NEDD9, SELE, TRIB1, and ZFP36." (PMID 27078000, 2016). "Overall, these findings link ATF3-mediated CCND1/2 activation to its SUMOylation and thereby imply this modification plays a functional role in CCND1/2 activation by ATF3 in prostate cancer PC3 and DU145 cells." (PMID 23591848, 2013). "Here we sought to explore the potential role of ATF3 SUMOylation on regulating the cellular proliferation of human prostate cancer cells." (PMID 23591848, 2013). "Many lines of evidence have characterized ATF3 as an oncogene in human breast and prostate cancers, as well as in Hodgkin lymphomas." (PMID 23591848, 2013). "Because SUMOylation is involved in ATF3-mediated CCND1/2 activation and CCND activity is required for cell cycle progression, we next investigated the potential role of SUMOylation of ATF3 in proliferation of prostate cancer cells." (PMID 23591848, 2013). "Recent study has reported that expression of metastasis suppressor gene, KAI1 gene, is involved in NDRG1 mediated metastasis suppression of prostate cancer through ATF3-NF-κB pathway." (PMID 22844455, 2012). "Enforced expression of ATF3 in prostate cancer cells induces cell proliferation and accelerates progression from the G1- to S-phase of the cell cycle." (PMID 21414204, 2011). "Previous studies indicate that overexpression of ATF3 results in increased apoptosis of prostate cancer cells, reduced tumour size of colorectal xenografts in nude mice, and increased apoptosis and reduced metastatic potential of ovarian cancer cells." (PMID 20565867, 2010).